RN7SL645P (RNA, 7SL, cytoplasmic 645, pseudogene)
Gene: Miscellaneous RNA gene on chromosome 16 (58,199,568 to 58,199,836, reverse strand). Ensembl gene ENSG00000240863.
Homologues: Orthologues: chimpanzee Metazoa_SRP (93% identical), macaque Metazoa_SRP (71% identical). Paralogues in human: RN7SL2 (85% identical), RN7SL1 (84% identical), RN7SL3 (83% identical), RN7SL357P (82% identical), RN7SL743P (82% identical), RN7SL326P (81% identical), RN7SL113P (80% identical), RN7SL60P (80% identical), Metazoa_SRP (80% identical), RN7SL220P (80% identical), RN7SL230P (80% identical), RN7SL296P (80% identical), and 702 more.